PTH (parathyroid hormone)
Diseases named in the same sentence as PTH in open-access papers (continued):
Sharing a sentence is not in itself a finding about the gene and the disease.
primary hyperparathyroidism (continued). "Primary hyperparathyroidism (pHPT) is characterized by the autonomous secretion of parathyroid hormone (PTH) by one or more parathyroid glands." (PMID 29403435, 2017). "In the literature, there are only a few studies evaluating third-generation PTH assays in patients with primary hyperparathyroidism." (PMID 27812604, 2016). "Primary hyperparathyroidism (pHPT) is a common endocrine disorder characterized by chronically elevated serum calcium and increased or inappropriately normal parathyroid hormone (PTH) concentrations." (PMID 27529699, 2016). "In primary hyperparathyroidism (PHP), excessive secretion of parathyroid hormone (PTH) from one or more hyperactive parathyroid glands causes elevated levels of blood Ca2+." (PMID 27548229, 2016). "In our cohort with primary hyperparathyroidism, the I-PTH and Bio-PTH assays identified elevated PTH levels in 87.8% and 92.7% of the patients, respectively." (PMID 27812604, 2016). "Primary hyperparathyroidism (PHPT) is due to oversecretion of PTH most commonly from a parathyroid adenoma." (PMID 27579039, 2016). "Primary hyperparathyroidism (pHPT) is a common endocrine disease characterized by excessive secretion of PTH and increased level of serum calcium." (PMID 26973719, 2016). "Primary hyperparathyroidism is a disease with various symptoms related to hypercalcemia due to excessive secretion of parathyroid hormone from a tumor or hyperplasia, such as adenoma and carcinoma, which arises in the parathyroid." (PMID 27056365, 2016). "Primary hyperparathyroidism is a rare disease characterized by excessive secretion of parathyroid hormone from parathyroid adenoma, hyperplasia, or malignancy." (PMID 27056365, 2016). "Primary hyperparathyroidism is usually characterized by a monoclonal parathyroid tumorsecreting excess parathyroid hormone (PTH)." (PMID 26865585, 2016). "From human clinical studies, it has become apparent that prolonged exposure to high PTH (p.e. primary hyperparathyroidism) indirectly increases osteoclast activity and decreases age-related osteoblast replicative activity, both contributing to bone loss." (PMID 27102152, 2016). "The results of biochemical analyses demonstrated the cardinal features of primary hyperparathyroidism including markedly elevated plasma Ca2+ concentration, suppressed plasma inorganic phosphate concentration, and markedly elevated serum PTH levels." (PMID 28018229, 2016). "Primary hyperparathyroidism (pHPT) is defined as an autonomous overproduction of parathyroid hormone (PTH)." (PMID 25773486, 2016). "In our cohort with primary hyperparathyroidism, one patient showed a higher PTH value using the Bio-PTH assay compared with the I-PTH." (PMID 27812604, 2016). "Among patients with primary hyperparathyroidism, serum PTH levels were elevated in 36 (87.8%) when measured with the I-PTH assay and in 38 (92.7%) when measured with the Bio-PTH assay." (PMID 27812604, 2016). "More specifically, primary hyperparathyroidism was defined based on normal, elevated or high PTH levels but elevated calcium levels and normal serum creatinine levels." (PMID 26010883, 2015). "Primary hyperparathyroidism is an endocrine disorder that develops as a result of autonomous production and secretion of parathyroid hormone (PTH) from parathyroid glands." (PMID 26834518, 2015). "We investigated the consequence of CaSR knock down in a mouse model in which exon-5 of the CaSR gene is globally ablated on a PTH-null background to prevent the development of catastrophic primary hyperparathyroidism." (PMID 25701758, 2015). "Primary hyperparathyroidism results in overproduction of PTH, mobilizing excess calcium to the bloodstream." (PMID 33530149, 2015). "Primary hyperparathyroidism is a disease characterized by excessive parathyroid cell proliferation and PTH secretion and occurs frequently in postmenopausal women." (PMID 25705702, 2015).
primary hyperparathyroidism (continued). "Primary hyperparathyroidism is an endocrinopathic condition characterized by hypersecretion of parathyroid hormone." (PMID 26179753, 2015). "In case the excess of albuminuria in the highest quintile was influenced by primary hyperparathyroidism, we excluded subjects with PTH levels outside the reference range (i.e. above the 95th centile of PTH, 75 pg/ml)." (PMID 24505486, 2014). "We investigated the relationship between postural changes and PTH levels in patients with primary hyperparathyroidism." (PMID 25254042, 2014). "The definition of primary hyperparathyroidism is the hypersecretion of parathyroid hormone by one or more parathyroid adenomas." (PMID 24685256, 2014). "Her laboratory data indicated primary hyperparathyroidism (serum calcium concentration 14.0 mg/dl, phosphate concentration 2.3 mg/dl, and intact parathyroid hormone (PTH) concentration 239 pg/ml)." (PMID 25379182, 2014). "Similar findings have also been seen in chronic elevations in PTH as in primary hyperparathyroidism." (PMID 25548714, 2014). "Primary hyperparathyroidism (PHPT) is characterized by overproduction of parathyroid hormone (PTH) from abnormal parathyroid gland(s)." (PMID 25241609, 2014). "Serum UA levels were significantly correlated with intact PTH levels among patients with primary hyperparathyroidism." (PMID 24340056, 2013). "Derangements in glucose metabolism in primary hyperparathyroidism are well described with increased PTH increasing glucose intolerance." (PMID 23596520, 2013). "Intraoperative PTH monitoring is a necessary adjunct to detect multiglandular disease in patients undergoing minimally invasive surgery for primary hyperparathyroidism." (PMID 24044556, 2013). "Primary hyperparathyroidism (PHPT) is described as an abnormally increased parathyroid hormone (PTH) production from parathyroid gland(s) in relation to the serum calcium." (PMID 24106573, 2013). "Serum PTH also correlated with an increase in systolic and diastolic blood pressure, and patients with mild primary hyperparathyroidism exhibited increased arterial stiffness." (PMID 23324569, 2013). "Primary hyperparathyroidism (PHPT) is characterized by elevated serum levels of parathyroid hormone (PTH) and calcium." (PMID 23418495, 2013). "An insufficient decrease in PTH indicates persisting primary hyperparathyroidism, leading to more extended (bilateral) exploration within the same session." (PMID 24044556, 2013). "Primary hyperparathyroidism (PHPT) is characterized by elevated calcium levels, inappropriately increased PTH levels, and is often associated with vitamin D deficiency." (PMID 22815708, 2012). "Primary hyperparathyroidism is a common endocrinopathy characterized by an inappropriate oversecretion of PTH." (PMID 22567348, 2011). "Biochemical diagnosis and confirmation of primary hyperparathyroidism is made by demonstrating elevated total serum or ionized calcium levels, and high intact PTH levels in the setting of normal renal function." (PMID 21776381, 2011). "Primary hyperparathyroidism (PHPT) is characterised by increased production of parathyroid hormone (PTH) resulting in elevated serum calcium levels." (PMID 21698093, 2011). "In such cases, the primary hyperparathyroidism usually results from the overproduction of parathyroid hormone by a parathyroid tumor." (PMID 19830212, 2009). "A study in adults with primary hyperparathyroidism illustrates the limitations of DXA in the setting of increased PTH." (PMID 17622566, 2007). "The diagnosis of primary hyperparathyroidism was confirmed by the elevated serum intact parathyroid hormone levels." (PMID 15160525, 2004). "The diagnosis of primary hyperparathyroidism was confirmed by elevated serum intact parathyroid hormone levels of 95 pg/ml." (PMID 15160525, 2004). "Furthermore, the model predicted that primary hyperparathyroidism elevates PTH, Ca2+, and calcitriol, leading to increased mean arterial pressure and bone loss." (PMID 41637481, 2026).
primary hyperparathyroidism (continued). "With these findings of primary hyperparathyroidism, he underwent subtotal parathyroidectomy (three parathyroid resections) and thymectomy, resulting in the normalization of serum calcium, phosphorus, and PTH levels." (PMID 40136120, 2025). "Parathyroid hormone (PTH) was suppressed (<10 pg/mL), ruling out primary hyperparathyroidism." (PMID 40438858, 2025). "In patients with primary hyperparathyroidism, calcium and PTH can be influenced by several factors including parathyroid adenoma size, 25-hydroxyvitamin D status, but also the calcium ‘set-point' for that individual within the reference range of 2.2 mmol/L–2.6 mmol/L." (PMID 40979160, 2025). "Primary hyperparathyroidism is an endocrine condition characterized by elevated parathyroid hormone, often with high calcium levels, though calcium may remain normal in some cases." (PMID 41480476, 2025). "In fact, chronic kidney disease-mineral and bone disorder, characterized by disturbances in calcium and phosphate levels with increase in PTH, can contribute not only to aortic stiffness but also to radial stiffness, similarly to what was observed in primary hyperparathyroidism." (PMID 39927753, 2025). "Recently, a new concept has been released, namely, familial isolated pancreatic NETs (FIPNET), that includes subjects carrying MEN1 pathogenic variants and a single clinical manifestation at the level of the pancreas with normal calcium/PTH levels (primary hyperparathyroidism-free phenotype)." (PMID 38928056, 2024). "Multivariate analysis of serum PTH in the primary hyperparathyroidism cohort." (PMID 39963179, 2024). "Nonparathyroid tumors with ectopic PTH production are an extremely rare cause of primary hyperparathyroidism, with very few cases being reported in literature." (PMID 39611185, 2024). "Nonparathyroid PTH-secreting neoplasms represent an extremely rare cause of primary hyperparathyroidism with only a few cases reported in literature." (PMID 39611185, 2024). "The initial hormonal panel was normal for the thyroid profile, but high serum calcium (of 3.11 mmol/L; normal ranges between 2.2 and 2.55 mmol/L) and PTH (of 152 pg/mL; normal ranges between 10 and 65 pg/mL) represented the biological confirmation of a primary hyperparathyroidism." (PMID 38791947, 2024). "Primary hyperparathyroidism represents the third most prevalent endocrine disease in the general population, consisting of an excessive secretion of parathyroid hormone from one or, more frequently, more of the parathyroid glands, leading to a dysregulation of calcium homeostasis." (PMID 39519139, 2024). "Primary hyperparathyroidism is characterized by excessive production of parathyroid hormone." (PMID 38975429, 2024). "This study evaluates the effectiveness of near-infrared fluorescence imaging (NIFI) as a replacement for intraoperative parathyroid hormone (ioPTH) measurement during minimally invasive parathyroidectomy (MIP) in patients with primary hyperparathyroidism due to parathyroid adenoma." (PMID 39682204, 2024). "In primary hyperparathyroidism, the level of parathyroid hormone (PTH) is elevated." (PMID 38804438, 2024). "Primary hyperparathyroidism patients should not restrict their dietary calcium intake, because calcium intake was found to be negatively associated with PTH levels, independent of other clinical parameters." (PMID 39963179, 2024). "In primary hyperparathyroidism (PHPT), there is increased secretion of PTH with resultant elevated blood calcium levels due to causes within the parathyroid gland, such as a single or multiple tumours which could be benign or malignant." (PMID 39061231, 2024). "Primary hyperparathyroidism (PHPT) is a common endocrinopathy, predominantly caused by a single parathyroid adenoma that is responsible for the excessive secretion of parathyroid hormone (PTH)—the hallmark of disease." (PMID 39519190, 2024).
primary hyperparathyroidism (continued). "Primary hyperparathyroidism (PHPT) is a common endocrine neoplastic disorder characterized by disrupted calcium homeostasis secondary to inappropriately elevated parathyroid hormone (PTH) secretion." (PMID 36992820, 2023). "We report a case of 72-year-old women with primary hyperparathyroidism who underwent fine-needle aspiration cytology (FNAC) of a parathyroid adenoma mistaken for a thyroid nodule followed by normalization of parathyroid hormone (PTH) and serum calcium levels." (PMID 37364141, 2023). "Another potential mechanism could be similar to that observed in primary hyperparathyroidism, characterised by chronically elevated parathyroid hormone concentrations, resulting in increased bone turnover, favouring bone resorption." (PMID 37690031, 2023). "Intraoperative PTH (iPTH), which involves the real-time sampling of circulating PTH levels to guide parathyroidectomy, improves surgical outcomes and is standard-of-care for managing primary hyperparathyroidism." (PMID 38239660, 2023). "Intra-operative parathyroid hormone (IOPTH) assay is an intraoperative tool which aids in detecting a significant fall in PTH levels during surgery predicting cure of primary hyperparathyroidism, while reducing the need for extensive four-gland dissection and associated post-operative complications." (PMID 37693360, 2023). "The postoperative re-evaluation conducted by the endocrinologists hypothesized a reactive increase of PTH and questioned the correctness of the initial diagnosis of primary hyperparathyroidism." (PMID 37174047, 2023). "In conclusion, this study demonstrated that 4D-CT has a high lesion-based sensitivity in patients with primary hyperparathyroidism and low baseline PTH levels but led to a relatively low rate of successful image-guided resection in patients with low baseline PTH levels." (PMID 37627880, 2023). "The idea of using a PTH analog as a bone-forming agent seems paradoxical since it is known that PTH is a hormone that primarily stimulates bone resorption, as observed in patients with primary hyperparathyroidism." (PMID 36382760, 2022). "About 80-90% of the patients with primary hyperparathyroidism tend to have elevated PTH levels." (PMID 35261825, 2022). "First described in 2003, normocalcemic primary hyperparathyroidism (NC-PHPT), is defined by persistently normal total and ionized calcium levels in the presence of high PTH levels after ruling out secondary causes of high PTH levels." (PMID 36382757, 2022). "Furthermore, primary hyperparathyroidism patients showed improvement in PTH and bone resorption and mineral density following vitamin D supplementation." (PMID 36556486, 2022). "It has been suggested that treatment of primary hyperparathyroidism, may have a positive effect on the cardiovascular system, reducing the activity of PTH and consequently aldosterone." (PMID 36389124, 2022). "Primary hyperparathyroidism (PHPT) is a condition characterized by disorders of calcium–phosphate metabolism and bone metabolism caused by pathological overproduction of parathyroid hormone (PTH)." (PMID 35052802, 2022). "Primary hyperparathyroidism is characterized by over production of PTH." (PMID 33881757, 2021). "Primary hyperparathyroidism (PHPT) is an endocrine and metabolic disease caused by excessive secretion of parathyroid hormone (PTH) by parathyroid tissue, classically manifested as a group of clinical manifestations, including nausea, vomiting, kidney stones, and bone lesions." (PMID 34840566, 2021). "The relationship between serum calcium (Ca) level to serum parathyroid hormone (PTH), phosphorus (P) levels and tissue properties of the parathyroid gland is unknown in primary hyperparathyroidism cases." (PMID 34797277, 2021). "PTH is known to simulate truncal fat distribution, thus centripetal obesity and related metabolic disturbances (i.e., metabolic syndrome) are often observed in primary hyperparathyroidism." (PMID 34490320, 2021).
primary hyperparathyroidism (continued). "Thus, in CAS, both the vitamin D and PTH levels will be low, whereas in primary hyperparathyroidism, both measurements are usually elevated." (PMID 33732556, 2021). "Also, elevated PTH levels have been found in some cases of CAS leading to misdiagnosis of the syndrome as primary hyperparathyroidism." (PMID 33732556, 2021). "The high PTH led us to consider primary hyperparathyroidism as a differential diagnosis." (PMID 33413267, 2021). "Both XLH and primary hyperparathyroidism may feature hypophosphatemia, renal stone formation, elevated PTH and FGF23 levels." (PMID 33815294, 2021). "However, if both hypercalcemia and/or elevated PTH values recur six months after normalization of serum calcium after surgery, the diagnosis of recurrent primary hyperparathyroidism (R-pHPT) is retained." (PMID 34943620, 2021). "Normal 25OHD levels accompanied by persistently elevated PTH and high serum calcium levels may be an indication of primary hyperparathyroidism hence the need to check PTH levels at baseline." (PMID 32743907, 2020). "Any disruptions in PTH production might induce various parathyroid abnormalities such as primary hyperparathyroidism (PHPT), characterized by excessive PTH release." (PMID 32283730, 2020). "Thus, the sensitivity of PTH in detecting asymptomatic primary hyperparathyroidism (PHPT) using the values recommended by the kit and established in this study was 64% and 93%, respectively (50% versus 87.5% for normocalcemic PHPT)." (PMID 30916167, 2019). "The only case of hypercalcemia was associated with increased PTH-related peptide, not PTH; hence, it was not primary hyperparathyroidism." (PMID 30693099, 2019). "Although three of her parathyroid glands had been removed, increased levels of calcium and parathyroid hormone were observed during the follow-up of the family, indicating recurrence or development of primary hyperparathyroidism in the remaining parathyroid gland." (PMID 30990521, 2019). "Moreover, the N-terminal PTH form can be overproduced in some patients with parathyroid carcinoma and severe primary hyperparathyroidism, where it represents a much larger proportion of the circulating PTH immunoreactivity in the third-generation PTH assay." (PMID 31637056, 2019). "We used Equation to examine TRCa/Ccr as a function of [PTH] in seven patients with primary hyperparathyroidism (PHPT), 29 patients with CKD (mean MDRD estimated GFR of 29.5 mL/min/1.73 m2, range 14–49), and 28 controls with normocalcemia and estimated GFR >60 mL/min/1.73 m2." (PMID 28445401, 2017). "Measurement of serum PTH levels is crucial in establishing the diagnosis of primary hyperparathyroidism, although the measurement may be normal or inconclusive in some patients." (PMID 27812604, 2016). "Our observations imply that canopies are likewise affected by PTH levels, a suggestion that is supported by findings in adult patients with primary hyperparathyroidism, in whom parathyroidectomy resulted in a 50% decrease in the proportion cancellous bone surface with canopy coverage." (PMID 27045269, 2016). "Excess parathyroid hormone results in an altered state of osseous metabolism involving bone resorption and tissue change known as osteitis fibrosa cystica, which is the end stage of primary hyperparathyroidism." (PMID 26179753, 2015). "Laboratory tests showed a serum calcium level of 11.8 mg/dL (normal range: 8.6–10.1), a phosphorus level of 2.4 mg/dL (normal range: 2.5–4.5), and a plasma intact parathyroid hormone (PTH) level of 427.2 pg/mL (normal range: <65.0), and a diagnosis of primary hyperparathyroidism was made." (PMID 26442164, 2015). "There have been a number of studies examining associations of CaSR polymorphisms with variables such as serum calcium concentrations, PTH levels, severity of primary hyperparathyroidism, calcium excretion, renal stones, fractures, bone mineral density, and risk of colon cancer." (PMID 25695075, 2015).